MYD88 (MYD88 innate immune signal transduction adaptor)
Diseases named in the same sentence as MYD88 in open-access papers (continued):
Sharing a sentence is not in itself a finding about the gene and the disease.
tumor (continued). "Additionally, high-mobility group box 1 (HMGB1) proteins derived from dead tumor cells trigger toll-like receptor 4 (TLR4) on DCs to produce type I IFNs through myeloid differentiation factor 88 (MyD88) signaling." (PMID 35292881, 2022). "Activation of TLR-4 may increase the production of factors that promote tumor development via the MyD88 pathway." (PMID 36520928, 2022). "The location of HMGB1 in the cytoplasm or extracellular space will promote the release of cytokines such as IL-6 and IL-8 by activating MAPK- and MyD88-dependent NF-KB pathways, thereby prompting tumor cell proliferation, angiogenesis, EMT, invasion, and metastasis." (PMID 35273678, 2022). "Animal studies are now underway to find out how tumor TLR4 expression levels may impact the anti-tumor efficacy of the anti-PAUF treatment, and to explore the synergistic anti-tumor efficacy of inhibition on both TLR4/MyD88 dependent PAUF and B7-H3." (PMID 36232715, 2022). "Indeed, F. nucleatum has been reported to promote chemoresistance in CRC patients through loss of tumor-suppressive miR-18a* and miR-4802 by activating TLR4/MyD88-dependent signaling." (PMID 35625485, 2022). "Yet, a recent study in mice shows that the TLR adaptor MyD88 (which is involved in innate immune responses) has a key role in promoting tumor development and that inflammation-induced carcinogenesis and 3mmune-editing can occur in the same tumor model." (PMID 35692318, 2022). "Specifically, MyD88 (IL-1β) was significantly increased compared the TM + T group which may indicate preconditioned exercise is able to protect against tumor-mediated cardiac inflammation that may serve to protect the heart." (PMID 36531941, 2022). "MyD88-dependent signaling is reported to control the expression of several key modifier genes of intestinal tumorigenesis and play a crucial role in both spontaneous and carcinogen-induced tumor development." (PMID 35309296, 2022). "MyD88−/− MDSCs fail to suppress the tumor antigen-specific T cell immune response." (PMID 35089465, 2022). "In addition, HMGB1 promotes the release of IL-6 and IL-8 by activating MAPK- and MyD88-dependent NF-κB pathways, resulting in promoted tumor proliferation, angiogenesis, EMT, invasion and metastasis." (PMID 35493517, 2022). "All these results demonstrate that the LPS fragments released from MRT+MH-treated Fn are capable of activating the macrophages into M1 polarization via the TLR4/MyD88/NF-κB pathway, which results in significant secretions of various cytokines against tumor cells in vitro." (PMID 36381212, 2022). "Enhanced levels of autophagy may be related to a tumor-mediated upregulation of cardiac beclin-1 expression and cardiac inflammation (MyD88), which lead to increased cardiac atrophy (FOXO1 signaling)." (PMID 36531941, 2022). "Further studies could also evaluate the transforming potential of Myd88 by adoptive transfer of LP-like tumor B-cells." (PMID 34017329, 2021). "Indeed, Otulinfl/flK14-Cre Myd88−/− mice (hereafter referred to as OTULINE-KO; Myd88−/−) were strongly protected from skin lesion development and most of these animals remained lesion-free until the age of about 14 weeks." (PMID 34625557, 2021). "In addition to FadA mechanisms, TLR4 activation by F. nucleatum’ LPS can plausible lead to the activation of Myd88 and NF-κB, which leads to oncogenic overexpression of miR21, resulting in dysregulated growth and infiltration of tumour tissue." (PMID 34949212, 2021). "Finally, CAR-NK cells engineered to express an artificial Myd88/CD40 signaling node display enhanced anti-tumor activity, likely through increased NF-κB activation." (PMID 33572260, 2021). "RNA sequencing dataset analyses detected that AAL may regulate the expression of JUN, TLR4, and MYD88 to suppress tumor proliferation." (PMID 34337031, 2021). "Indeed, circulating levels of LCN2 are significantly reduced in both Myd88 and Il-6 knockout tumor-bearing mice." (PMID 33824339, 2021).
tumor (continued). "Next, we assessed the relevance of MYD88 activation in tumour development." (PMID 33597599, 2021). "Furthermore, MyD88 deficiency in the ApcMin/+ mouse model of spontaneous intestinal tumorigenesis demonstrated that MyD88 signaling substantially contributes to tumor growth." (PMID 33557139, 2021). "In addition, specific CD44+/MyD88+ epithelial ovarian cancer stem cells have been shown to be responsible for tumor initiation, even after surgical and chemotherapeutic treatment." (PMID 34439332, 2021). "Moreover, MYD88 and CD79B were identified as cancer driver genes in the high-risk group, which is in good agreement with the previous findings that MYD88 and CD79B mutations have been associated with tumor response and survival in DLBCL patients." (PMID 34745101, 2021). "TLR4 signaling pathway is a classic regulatory pathway, polysaccharides promote the production of cytokines, regulate immune response and anti-tumor by activates the cascade of immunoregulation pathway and key downstream transcription factors, such as MyD88 and NF-κBs." (PMID 34641277, 2021). "Tumor-derived Exos could deliver MyD88, Hsp72, MICA∗008, HER2, miR-223, and let-7 miRNA family to promote the development of tumor through regulating angiogenesis and cell growth of tumor." (PMID 33834074, 2021). "RNA sequencing and TCGA dataset analyses detected that AAL may regulate the expression of JUN, TLR4, and MYD88 to suppress tumor proliferation." (PMID 34337031, 2021). "WNT5a can also specifically activate the TLR/MyD88/p50 pathway in bone marrow monocytes and promote the synthesis of anti-inflammatory cytokines such as IL-10 and the tolerance phenotype, thus forming an immunosuppressive tumor microenvironment." (PMID 34565373, 2021). "The loss of MyD88 signaling in B cells resulted in increased CD8+ T cell effector responses in the spleen but not in the tumor nor the tumor-draining lymph node upon tumor challenge, suggesting insufficient T cell priming." (PMID 35046933, 2021). "Similarly, in our melanoma models, exogenously administered IL-33 activated mDCs in the TME, promoting cross-presentation of tumor antigen in a ST2/MyD88/STAT1-dependent fashion and restoring a competent anti-tumor T cell activity." (PMID 34209038, 2021). "We speculated that during tumor progression the antitumor role of MyD88 affects tumor differentiation to a certain degree resulting in well-/moderately differentiated tumors with higher MyD88 expression." (PMID 32477927, 2020). "The molecular basis for exceptional responses to ibrutinib in DLBCLs has been explained on cell lines and tumor biopsies by the formation of a multiprotein super-complex formed by MYD88, TLR9, and the BCR, whose presence differentiate ibrutinib responders from non-responders." (PMID 33050534, 2020). "Finally, in ovarian cancer, TLR2 expressed on CD44+/MyD88+ CSCs promotes their self-renewal and induces the secretion of pro-inflammatory cytokines, thus actively contributing to tumor repair following injury induced by surgery or chemotherapy." (PMID 33321934, 2020). "Moreover, HJ901 prevented tumor growth and downregulated the NF-κB and JAK2-STAT3 signaling pathways in a DLBCL xenograft mouse model with the MyD88 L265P mutation." (PMID 32391356, 2020). "MyD88 plays an important role in tumor immunity by regulating NF-κB–mediated functions." (PMID 32477927, 2020). "Moreover, the expressions of TLR4, MyD88, and P-NF-κB p65 in subcutaneous tumor tissues from the USP13 knockdown group were prominently lower than those in the control group (P < 0.05)." (PMID 33195243, 2020).
tumor (continued). "The results showed that blockade of HMGB1 signaling diminished the antitumor effect of β-lap, indicating that β-lap may induce HMGB1 release in the tumor microenvironment to enhance innate response via a TLR4/MyD88 pathway." (PMID 31324798, 2019). "Moreover, concomitant overexpression of defensin and Myd88-IR or Imd-IR in the fat body of dlg larvae was sufficient to significantly rescue the tumour volume and tumour cell death phenotypes resulting from fat body knockdown of Myd88 or Imd in dlg animals." (PMID 31358113, 2019). "This non-invasive, simple, inclusive NGS method may provide powerful tools to monitor tumor burden during patients’ clinical course, as well as to further investigate the clinical implications of MYD88 L265P in IgM MGUS and WM patients." (PMID 31483817, 2019). "Our non-invasive, simple NGS method has the potential to detect MYD88 L265P mutations in PBMCs of IgM MGUS and WM patients, which may especially utilized for monitoring minimal residual tumor burden after treatment." (PMID 31483817, 2019). "Similarly, in Tlr4−/− and Myd88−/− mice there were much less tumor reactive T cells in the control group compared with that in WT mice." (PMID 31324798, 2019). "More relevant to time of day, some inflammatory mediators (Myd88, Cd4, Tlr9, Cd38, C3, Ly96) demonstrated nyctohemeral (day versus night) differences in control brain tissues that were abolished in tumor-bearing and/or tumor-resected mice." (PMID 31019214, 2019). "Similarly, the antitumor effect of β-lap in NQO1-overexpressing B16 tumor models was also abolished in Myd88−/− mice or Ifnαr−/− mice." (PMID 31324798, 2019). "Moreover, β-lap-induced tumor regression disappeared in MC38 bearing Myd88−/− mice with the same therapeutic schema." (PMID 31324798, 2019). "Unlike the previous reports, MYD88 L265P allele frequency in PBMCs did not correlate with BM tumor burden, serum IgM, and hemoglobin levels in our study cohort." (PMID 31483817, 2019). "Therefore, miRNAs can regulate NF-κB activities by targeting MyD88, which has a very important significance for tumor development." (PMID 29616037, 2018). "Moreover, both TNF-α and IL-6 in the serum of the C57BL/6J (MyD88+/+) tumor-bearing mice stimulated by APS and LPS were obviously higher than those in NS and ADM groups (P< 0.05)." (PMID 28303957, 2017). "However, the precise mechanisms whereby MyD88 act intrinsically in tumor cells to sustain cancer progression remain poorly understood." (PMID 28662055, 2017). "In consideration of the significant tumor-promoting function of Lnc-Myd88 in vitro and in vivo, we wondered whether the effect of Lnc-Myd88 was related with the neighbor gene Myd88." (PMID 29022910, 2017). "Pretreatment of tumor cells with LPS sensitized MyD88-positive cells (but not MyD88-deficient) to docetaxel cytotoxicity in both drug-naive and drug-resistant cells." (PMID 28915246, 2017). "In this study, a total of 12 genes, including TRAF, IRAK, TAB2, TLR, IL1R, and MYD88, harboured nonsilent mutations, indicating the activation of the NF-kB signalling pathway in tumour cells." (PMID 29127303, 2017). "Several lines of evidence have suggested that MyD88 plays an important role in tumor development." (PMID 28662055, 2017). "Based on the functional differences observed between SCR and shMyD88 cell lines, we further investigated whether MyD88 knockdown affected tumorigenicity in vivo by using a mouse tumor model." (PMID 28662055, 2017). "All in all we came a conclusion that Lnc-Myd88 might promote tumor progression through upregulating Myd88 and then activating the NF-κB and PI3K/AKT signal pathways." (PMID 29022910, 2017). "In C57BL/10J (TLR4+/+wild-type) and C57BL/6J (MyD88+/+wild-type) tumor-bearing mice, the tumor apoptosis rate, immune organ indexes and the levels of TNF-α, IL-1β and IL-6 in blood increased and the tumor weight decreased by oral administration of APS for 25 days." (PMID 28303957, 2017).
tumor (continued). "As reported in previous studies, enhanced Myd88 could not only evade apoptotic stimulation and promote cell-cycle progress but also confer tumor cells with strengthened abilities of proliferation, migration and invasion especially in HCC." (PMID 29022910, 2017). "The keratinocyte-derived IL-1α may be involved in (MyD88-dependent) induction of IL-1β, with IL-1β induction by IL-1 reported previously and tumour-derived IL-1β also shown to recruit neutrophils to the tumour." (PMID 27100888, 2016). "Human EOC cells usurp or hijack TLR4/MyD88 signaling pathway that considerably activates NF-κB and Akt pathways, which trigger expression of immunosuppressive molecules resulting in immune incompetence in the tumor microenvironment." (PMID 27118139, 2016). "A number of hypothesis have been formulated along the way, but the overarching one would be that inhibition of ERK1/2 MAPK activation would prevent tumor growth downstream of MYD88[L265]." (PMID 27303665, 2016). "Previous studies showed that the anti-tumor effects of S. enterica depend on the functional role of the MyD88-TLR pathway, and S. enterica enhances anti-tumor immunity by inhibiting tumor indoleamine 2, 3-dioxygenase 1 expression and inducing gap junctions in tumors." (PMID 27835896, 2016). "Despite the recognized importance of MyD88 signaling in driving high level IL-12 production in response to T. gondii infection, vaccination of MyD88-/- mice bearing ID8DV tumors provided a therapeutic benefit equivalent to vaccination of wild-type tumor-bearing mice." (PMID 27447180, 2016). "MyD88-deficiency in macrophages reduced MCP-1 expression and production by LLC cells in vitro, but MyD88-deficiency did not reduce serum MCP-1 levels or LLC tumor volumes as effectively as TNFα-deficiency in vivo." (PMID 26167165, 2015). "We identified mutations that seem to be heterozygous and clonal as they show allele frequencies of >40 % in the WES and 46–53 % in the validation experiments (NOTCH2, SMYD1, MYD88), with the proximity to 50 % providing an indirect evidence for high tumor cell purity." (PMID 26498442, 2015). "Additionally, LPS activation of TLR4/MyD88 signaling has been shown to play an important role in pancreatic cancer tumor growth and migration, and blockade of this pathway decreases tumor invasive ability." (PMID 26172047, 2015). "In addition, mice with Bacteroides vulgatus or dual knockout mice (Il10- and MyD88-deficient mice) treated with AOM showed reduced transcription of Il12p40 and TNF-α and remained tumor-free." (PMID 25076949, 2014). "MyD88 staining was primarily observed in the cytoplasm and nuclei of tumor cells." (PMID 25360699, 2014). "In addition, elevated expression of MAP1S in response to flagellin feed-back regulated tumor inflammatory microenvironment in the late stages of TLR5 signaling through degradation of MyD88 in autophagy process." (PMID 24466264, 2014). "Similarly, median time to recurrence for MyD88 positive tumours was 13 months (n = 21), compared to 31 months if MyD88 negative (n = 18); p = 0.02." (PMID 24977712, 2014). "Furthermore, reduced expression of c-Myc has been reported in Apcmin/+/Myd88-/- of both normal and tumor mice." (PMID 25076949, 2014). "Recent reports suggest that MyD88 expression of EOC cells may be associated with the invasion and metastasis of tumor by acquisition of epithelial mesenchymal transition(EMT) phenotype." (PMID 22533866, 2012). "MyD88 expression was observed in benign cysts, but greatest in borderline and malignant tumours." (PMID 22533866, 2012). "In addition, MyD88 has been shown to be pivotal for the resistance to paclitaxel and the promotion of tumour progression in patients with EOC." (PMID 22533866, 2012). "The expression levels of TLR4 and MyD88 in situ were correlated with tumor differentiation." (PMID 22583829, 2012). "The expression pattern of MyD88 in OSCC tumor tissues was similar to that of TLR4 (p = 0.034)." (PMID 22583829, 2012).
tumor (continued). "Of note, MyD88−/−/ApcMin/+ mice exhibited increased IEC apoptosis and it is possible that deficiency of MyD88 impaired stability of its death domain-partner FADD to enhance recruitment of caspase 8, promoting IEC turnover and delaying tumor progression." (PMID 20803699, 2010). "It was recently reported that TLR4/MyD88 signalling drives tumour growth in numerous organs." (PMID 20145615, 2010). "In addition, MyD88 is a positive regulator of chemically induced tumours of both the skin and connective tissue." (PMID 20145615, 2010). "In addition, the involvement of TLR signalling through MyD88 in tumour growth and progression has been demonstrated in an Apcmin/+ mice model." (PMID 20145615, 2010). "However, because the pro-inflammatory cytokine il-1β uses myd88 to signal downstream of its receptor, a formal demonstration that bacterial signalling factors participate in tumour progression is still needed in this model." (PMID 19672421, 2009). "Individuals exhibiting heightened MyD88 expression displayed a tumor microenvironment that fosters immune activity, marked by an upsurge in immune cells that suppress cancer, such as M1 macrophages, and a concurrent reduction in those that may promote cancer development, including M2 macrophages." (PMID 39744584, 2025). "Research by Jie Xu and colleagues showed that SeNPs significantly activated the Tlr4/Myd88/NF-κB signaling pathway, leading to the conversion of M2 macrophages into M1 macrophages and effectively stimulating an anti-tumor immune response in mice with the H22 tumor model." (PMID 40182029, 2025). "Therefore, MyD88 may play a critical role in cancer progression by acting as a novel tumor marker and altering the tumor immune microenvironment, signaling, and binding of substrate proteins." (PMID 38785969, 2024). "However, the specific role of MyD88 in regulating tumor immunity and tumorigenic mechanisms remains unclear." (PMID 38785969, 2024). "Furthermore, there is evidence of a connection between MyD88 and tumor cell resistance." (PMID 38347830, 2024). "Therefore, MyD88 could serve as a novel tumor biomarker and is a promising target for cancer therapy." (PMID 38785969, 2024). "Interestingly, high MyD88 protein levels irrespective of mutation status in DLBCL are associated with tumor recurrence and shortened survival in patients." (PMID 36982699, 2023). "However, only MyD88 supports tumor infiltration into the brain slice." (PMID 36224342, 2022). "Although these tumors had the same morphology, phenotype, cytogenetic characteristics, clonal relationship and MYD88 L265P mutations, the relapsed tumor had a distinct CD79B Y196S mutation, suggesting that both tumors might have evolved from a common progenitor clone with MYD88 L265P mutations." (PMID 33996566, 2021). "Importantly, CD8α:MyD88 costimulation functioned in a TCR-dependent but TLR ligand independent manner resulting in enhanced activity against weakly immunogenic or lowly expressed tumor antigens." (PMID 34344725, 2021). "Therefore, the ICA may be an effective drug to attenuate the TLR4/MyD88/NF-κB and Wnt/β-catenin signaling pathways to suppress tumor cell proliferation in xenograft in mice models." (PMID 33849528, 2021). "Additionally, TLR stimulation has been shown to block the suppressive effects of MDSCs in tumor-bearing mice, indicating that MyD88 signaling may play a role in the abrogation of the suppressive effects of MDSCs." (PMID 32932705, 2020).